ACHE (acetylcholinesterase (Yt blood group))
Diseases named in the same sentence as ACHE in open-access papers (continued):
Sharing a sentence is not in itself a finding about the gene and the disease.
Alzheimer disease (continued). "Decreases in the neurotransmitter levels in the cholinergic synapses within certain regions of the brain are caused by acetylcholine and butyrylcholine hydrolysis, caused by AChE and BChE; therefore, their inhibition by these compounds is a suitable therapy for Alzheimer’s disease." (PMID 38893333, 2024). "Altered AChE activity has been associated with neurological disorders like Alzheimer’s disease." (PMID 38190061, 2024). "Alzheimer’s disease is mainly caused by cholinesterase (AChE and BuChE) enzymes." (PMID 37894494, 2023). "In addition, positron emission tomography and autopsy studies revealed a loss of AChE in the forebrain of Alzheimer’s disease patients." (PMID 36449200, 2023). "In Alzheimer’s disease, there is a loss of cholinergic neurons and the neurotransmitter itself; therefore, the inhibition of the AChE enzyme could help treat symptoms associated with memory and cognitive function." (PMID 37512512, 2023). "Generally, there are three major hypothesis, i.e., AChE, amyloid, and tau, which are primarily implicated in Alzheimer’s disease management and prevention." (PMID 37554984, 2023). "In previous studies, it has been reported that antioxidant molecules inhibit acetylcholinesterase (AChE), butyrylcholinesterase (BChE), and carbonic anhydrase (CA) enzymes, which are linked to some common diseases including epilepsy, glaucoma, and Alzheimer’s disease (AD)." (PMID 36986640, 2023). "Moreover, low levels of acetylcholine in the synapses due to increased AChE activity have been linked to memory loss commonly seen in Alzheimer’s disease (AD)." (PMID 35009126, 2022). "The active triad is the major focus for the regulated reduction of AChE in patients with acetylcholine deficiency, such as those with Alzheimer’s disease or myasthenia gravis, which is described by varying muscle weakness and exhaustion as a result of a loss of receptors." (PMID 35897660, 2022). "Treatments with AChE inhibitors, including galantamine have been shown to reduce the risk of acute myocardial infarction and death in a nationwide cohort of subjects diagnosed with Alzheimer's dementia." (PMID 33776997, 2021). "Acetyl cholinesterase (AChE) is an important therapeutic target to alleviate the deterioration of cholinergic neurons in the brain and the loss of neurotransmission, i.e., one of the major causes of Alzheimer’s disease." (PMID 34200152, 2021). "Degradation of neurotransmitters by cholinesterases (ChEs), including acetylcholinesterase (AChE) and butyrylcholinesterase (BChE), have been hypothesized as a cause of Alzheimer’s disease (AD) occurrence." (PMID 33670795, 2021). "In addition, an age-dependent decline in acetylcholinesterase (AChE), the enzyme responsible for acetylcholine hydrolysis, is associated with reduced AChE in patients with Alzheimer’s disease." (PMID 32954291, 2020). "Decrease in the activity of AChE in cortex and hippocampus of brain have been implicated in dementia and cognitive impairment in Alzheimer’s disease (AD) patients, which may thus explain the mechanism underlying the cognitive decline in CKD." (PMID 30816118, 2019). "In post-mortem analysis of patients with Alzheimer's Disease, there is a clear loss of cholinergic neurons, and a significant reduction in cholinergic enzymes, choline acetyltransferase (ChAT) and acetyl-cholinesterase (AChE)." (PMID 31481864, 2019). "The plant extracts effects mentioned, like gastro-intestinal propelling and blood cholesterol reduction, in addition to its association with Alzheimer’s Disease, have guided us to evaluate the activities of AChE and 3-hydroxy-3-methyl-glutaryl-coenzyme A reductase (HMGR)." (PMID 31652501, 2019). "The accumulation of data on acetylcholine deficiency and the decrease of acetylcholinesterase (AChE) in the brain of patients with Alzheimer’s disease (AD) provided the basis for the cholinergic hypothesis of AD." (PMID 31349637, 2019).
Alzheimer disease (continued). "Therefore, snake venom AChE is the best source of drug design for the treatment of Alzheimer’s disease, which is due to deficiency of neurotransmitter acetylcholine." (PMID 30186576, 2018). "Moreover, this plant can be used as a therapeutic agent to cure Alzheimer’s disease due to inhibition of AChE activity, which causes enhancement in the amount of neurotransmitter (acetylcholine) in patient." (PMID 30186576, 2018). "In view of its potent AChE inhibitory activity, linarin may be a promising therapeutic agent for the treatment of some diseases associated with AChE, such as glaucoma, myasthenia gravis, gastric motility and Alzheimer’s disease." (PMID 26330885, 2015). "It is known that one of the characteristic alterations that occur in Alzheimer's disease is the loss of acetylcholinesterase (AChE) activity, the enzyme that is responsible for acetylcholine hydrolysis, from both cholinergic and non-cholinergic neurons of the brain." (PMID 25415340, 2014). "In recent years, acetylcholinesterase (AChE) inhibitors like donepezil with prevention of acetylcholine hydrolysis can enhance the duration of action of acetylcholine in synaptic cleft and improve the dementia associated with Alzheimer’s disease." (PMID 23758724, 2013). "Moreover, carvacrol exerts a strong acetylcholinesterase (AChE) inhibitory effect due to the molecule hydroxyl group binding to AChE, causing a loss of function of AChE, thus suggesting a possible application in Alzheimer’s disease treatment." (PMID 23708230, 2013). "Current drugs targeting AChE, e.g., to treat symptoms of Alzheimer's disease, are associated with adverse effects, and/or low efficacy, warranting searches for new chemical skeletons that could have different pharmacodynamic and pharmacokinetic profiles." (PMID 22140425, 2011). "A profound change in blood-brain barrier permeability associated with Alzheimer's disease, may be facilitating the movement of AChE monomers through CSF/brain to the blood." (PMID 20090844, 2010). "In Alzheimer disease (AD)–Salivary AChE activity may prove to be a useful marker of AD–associated changesin central cholinergic activity and the responsiveness of patients to treatment with AChE inhibitors." (PMID 20108531, 2009). "Accordingly, recent studies have explored the roles of the two AChE variants in the response to neuronal injury and neurodegeneration, physical trauma, and Alzheimer disease." (PMID 17366821, 2007). "Previous studies have suggested that T14, a 14-amino-acid peptide derived from acetylcholinesterase (AChE), functions as an activity-dependent signalling molecule with key roles in brain development, and its dysregulation has been linked to neurodegeneration in Alzheimer’s disease." (PMID 40565249, 2025). "AChE is responsible for the hydrolysis of acetylcholine (ACh), an important compound in neurotransmission (associated with learning and memory functions), thus the use of AChE inhibitors is one of the currently available treatment options for Alzheimer’s disease." (PMID 36830094, 2023). "Additionally, the inhibition effects of Schiff bases and hydrazineylidene derivatives (16 and 17) were determined against some metabolic enzymes including AChE, BChE, hCA I, and hCA II enzymes, which are linked to some global disorders including Alzheimer’s disease (AD), epilepsy, and glaucoma." (PMID 36986640, 2023). "These would help proffer a solution to the menace of ‘Alzheimer’s disease caused by the overexpression and dysregulation of AChE and BChE, which could subsequently serve as a corrective measure to the degree of alteration and mutation of proteins at the neuromuscular junction." (PMID 34592924, 2021). "This article describes acetylcholinesterase (AChE), an enzyme involved in parasympathetic neurotransmission, its activity, and how its inhibition can be pharmacologically useful for treating dementia, caused by Alzheimer’s disease, or as a warfare method due to the action of nerve agents." (PMID 32155996, 2020).
Alzheimer disease (continued). "Moreover, the U.S.A. National Academy of Sciences NRC previously reported that F− downregulates AChE and suggested that this action may contribute to increases the risk of developing Alzheimer’s disease." (PMID 31010095, 2019). "Alzheimer's disease (AD) is a progressive neurodegenerative disorder characterized in part by cholinergic dysfunction resulting from excessive acetylcholinesterase (AChE) activity." (PMID 42221029, 2026). "A series of novel coumarin-triazole hybrids (12a-s) were synthesized and evaluated for their inhibitory activities against cholinesterase including acetylcholinesterase (AChE) and butyrylcholinesterase (BChE), enzymes related to Alzheimer's disease." (PMID 42017160, 2026). "This study evaluated 40 phytocompounds from the Astragalus zederbaueri plant as potential AChE inhibitors for Alzheimer's disease." (PMID 41961910, 2026). "These compounds act as antioxidants and inhibit acetylcholinesterase (AChE) as well as β-amyloid peptide aggregation, both of which are key pathological features of Alzheimer′s disease." (PMID 41226143, 2025). "From a neurological perspective, inhibition of acetylcholinesterase (AChE) and butyrylcholinesterase (BChE) is considered a relevant target in the management of neurodegenerative conditions such as Alzheimer’s disease." (PMID 41008939, 2025). "In conclusion, the tubular form withthe stopper shows great potential for Alzheimer’s disease treatment,as it blocks the entrance cavity of the AChE active pocket and enhancesthe stability of the inactive BACE-1 enzyme." (PMID 40787376, 2025). "In vitro, the inhibitory action of BHA on AChE activity in isolated brain homogenates relates to Alzheimer’s disease (AD)." (PMID 40700163, 2025). "Similar to this, it has been demonstrated that the coumarin molecule marmelosin inhibits AChE, a crucial mechanism for enhancing cognitive function and managing Alzheimer's disease." (PMID 40535825, 2025). "Galantamine (GAL), an alkaloid used clinically for the symptomatic treatment of Alzheimer’s disease (AD), acts through reversible inhibition of AChE and modulation of nicotinic receptors, thereby facilitating cholinergic neurotransmission." (PMID 41155598, 2025). "These important enzymes have been linked to a wide range of human diseases, including diabetes for α-amylase, Parkinson’s disease for tyrosinase, and Alzheimer’s disease for AChE and BChE." (PMID 41393958, 2025). "Hup A was initially identified as an inhibitor of acetylcholinesterase (AChE) based on Chinese databases, and it has been utilized in the treatment of cognitive disorders related to memory deficits, including Alzheimer’s disease and other types of dementia." (PMID 40474977, 2025). "In conclusion, thetubular form with a stopper group shows great potential for the treatmentof Alzheimer’s disease, as it blocks the entrance cavity ofthe AChE active pocket for the substrate and increases the stabilityof the inactive BACE-1 enzyme." (PMID 40787376, 2025). "Molecular docking has been extensively used to identify acetylcholinesterase (AChE) inhibitors and analyze the interaction of previously known compounds, aiming to develop more effective drugs for treating Alzheimer’s disease." (PMID 40332446, 2025). "The usage of dual acetylcholinesterase (AChE) monoamine oxidase B inhibitors is a novel strategy in treating Alzheimer's disease." (PMID 41181006, 2025). "During the progression of Alzheimer’s disease, the activity of AChE in the temporal lobe and the hippocampus decreases by 67% below average levels, whilst the activity of BuChE increases by up to 165% of normal levels." (PMID 40429850, 2025). "The present study sheds light on evaluating and designing novel pyrazole and benzofuran-based derivatives as potent acetylcholinesterase (AChE) inhibitors with improved antioxidant features to manage Alzheimer’s disease." (PMID 40475253, 2025).
Alzheimer disease (continued). "This study will promote the high-quality utilization of yellowfin tuna side products and provide important insights into the use of marine-derived AChE inhibitory peptides in Alzheimer’s disease." (PMID 39997199, 2025). "Existing research on AM primarily focuses on preclinical models, where its extracts have demonstrated acetylcholinesterase (AChE) inhibitory activity, suggesting potential benefits for Alzheimer's disease." (PMID 40535825, 2025). "Three AChE inhibitors—donepezil, rivastigmine, galantamine, and memantine—are clinically licensed for Alzheimer’s disease (AD)." (PMID 40430359, 2025). "In Alzheimer’s disease, while AChE activity decreases in the hippocampus and temporal cortex, the action of BChE increases in these regions, highlighting the significant role of BChE in regulating brain acetylcholine levels." (PMID 40143145, 2025). "The pathological mechanisms of Alzheimer’s disease involve the dysfunction of acetylcholinesterase (AChE) and β-secretase (BACE1)." (PMID 40932246, 2025). "Huperzine A (HupA) can alleviate Alzheimer’s disease due to its reversible inhibition of acetylcholinesterase (AChE)." (PMID 40649224, 2025). "In animal models of Alzheimer’s disease, plant sterols (β-sitosterol and stigmasterol) improve cognitive function by reducing acetylcholinesterase or acetylcholinesterase (AChE/BChE) activity and free radical load in the cerebral cortex and hippocampus." (PMID 41009787, 2025). "Approved anti-alzheimer’s disease drugs, including acetylcholinesterase (AChE) inhibitors like tacrine, donepezil, and N-methyl-D-aspartate (NMDA) receptor antagonists, can alleviate symptoms, particularly in the early to moderate stages of the disease." (PMID 40771195, 2025). "Overall, compound 3k shows significant promise as a therapeutic agent for Alzheimer’s disease due to its potent inhibitory activity and stable interactions with AChE." (PMID 40649306, 2025). "flowers, which contain Mesuaferrone A and B as major constituents, have demonstrated anti-AChE activity relevant to the pathogenesis of Alzheimer’s disease." (PMID 40243991, 2025). "Inhibition of AChE and BChE, orthosteric or allosteric, or partial agonism of M1 mAChR are correlated with Alzheimer’s disease (AD) symptoms improvement." (PMID 40143145, 2025). "Recently, dual sEH/AchE inhibitors have been synthesized for targeting Alzheimer’s disease by linking 6-chlorotacrine or huperine Y, a chiral derivative of tacrine, to the propanoyl group of TPPU." (PMID 41007636, 2025). "Among acetylcholinesterase (AChE) inhibitors, donepezil, widely used in Alzheimer’s disease, has shown promising effects in retinal neurodegeneration." (PMID 40943905, 2025). "As an AChE inhibitor, galantamine has long been used to treat the cognitive impairments in Alzheimer’s disease." (PMID 39824806, 2025). "Inhibiting AChE is currently a common pharmacological strategy for several conditions, such as myasthenia gravis, postoperative use, Alzheimer’s disease, and certain eye diseases." (PMID 40846775, 2025). "The impact of structural bioinformatics on AChE pharmacology is not limited to Alzheimer’s disease but has also extended to other biomedical applications, such as the development of antidotes against neurotoxins and organophosphate pesticides." (PMID 40332446, 2025). "By inhibiting key enzymes like acetylcholinesterase (AChE), butyrylcholinesterase (BChE), and glycogen synthase kinase-3β (GSK-3β), they help prevent the formation of β-amyloid plaques, a hallmark of Alzheimer’s disease." (PMID 40333636, 2025). "Despite being the most promising target in the pathology of Alzheimer’s disease, the AChE drugs approved by the FDA, namely, rivastigmine, donepezil, and galantamine, only provide symptomatic treatment." (PMID 40733241, 2025). "For example, ACHE is a target of anticholinesterase inhibitors such as galantamine and rivastigmine, which are well-established treatments for Alzheimer’s disease." (PMID 41001519, 2025).
Alzheimer disease (continued). "Rivastigmine is noted for its dual inhibition of both AChE and butyrylcholinesterase (BChE), which is beneficial, given that butyrylcholinesterase activity tends to increase in the later stages of Alzheimer’s disease, while AChE activity decreases." (PMID 40243991, 2025). "The significant inhibition of AChE and BChE points to the possibility of using these compounds in the treatment of neurodegenerative diseases, such as Alzheimer’s disease, through a mechanism of inhibition of acetylcholine-degrading enzymes." (PMID 40286078, 2025). "This inhibitory capacity is relevant due to its potential application in the treatment of neurodegenerative diseases such as Alzheimer’s disease, as AChE inhibition favors the transmission of nerve signals by maintaining adequate levels of acetylcholine." (PMID 40649231, 2025). "AChE inhibitors, such as donepezil, are used to alleviate symptoms of Alzheimer’s disease by increasing acetylcholine levels and improving nerve function." (PMID 39860266, 2025). "Anti-AChE activity still represents a key player in Alzheimer’s disease (AD) therapy, even if other mechanisms have been evoked as more valuable treatment strategies." (PMID 40333852, 2025). "Molecular docking revealed that tormentic acid interacts strongly with critical residues in the AChE active site, suggesting a mechanism similar to those of the reported anti-AChE agents used in Alzheimer’s disease management." (PMID 40298661, 2025). "Literature suggests that phenol- and flavonoid-rich extracts can serve as natural AChE inhibitors, offering potential therapy for cognitive disorders like Alzheimer’s disease." (PMID 40497956, 2025). "AChE and BChE are two important targets in the treatment of Alzheimer's disease (AD), and α-glucosidase is a carbohydrate-hydrolyzing enzyme with therapeutic importance in diabetes." (PMID 40860056, 2025). "Molecular docking studies have become an essential tool in the field of drug discovery, particularly for identifying potential inhibitors of AChE, an enzyme critically involved in the pathophysiology of Alzheimer’s disease." (PMID 40243991, 2025). "In Alzheimer’s disease (AD) patients, the levels of ACh are reduced in synaptic junctions; hence, inhibition of AChE is desirable to maintain the normal ACh levels." (PMID 40807313, 2025). "T. terrestris extracts, particularly ethanol extracts, have been shown to have a substantial inhibitory effect against α-glycosidase and cholinesterases (AChE and BChE), which are essential for managing diabetes and Alzheimer’s disease, respectively." (PMID 41465738, 2025). "The antioxidant and the inhibition capacity of two brain enzymes, cholinesterases (AChE and BuChE), involved in the pathogenesis of Alzheimer’s disease, were also evaluated in the final prototypes." (PMID 40278268, 2025). "Therapeutic strategies for Alzheimer’s disease (AD) often involve inhibiting acetylcholinesterase (AChE), underscoring the need for novel inhibitors with high selectivity and minimal side effects." (PMID 40017724, 2025). "Inhibition of acetylcholinesterase (AChE) can enhance cholinergic transmission, which is beneficial in conditions like Alzheimer’s disease where cholinergic deficits are prominent." (PMID 40729025, 2025). "ADMET (absorption, distribution, metabolism, excretion, and toxicity) prediction plays a critical role in the development of AChE inhibitors derived from natural products, particularly in therapeutic strategies against Alzheimer’s disease." (PMID 40243991, 2025). "Cholinesterase enzymes (BuChE and AChE) are privileged biological targets for the symptomatic treatment of Alzheimer's disease." (PMID 40034281, 2025). "Fasciculins are very strong inhibitors of acetylcholinesterase (AChE) and hence offer promise in multi-target drugs and as treatments for treating Alzheimer’s disease." (PMID 41155192, 2025).